SEMA3A (semaphorin 3A)
Diseases named in the same sentence as SEMA3A in open-access papers (continued):
Sharing a sentence is not in itself a finding about the gene and the disease.
tumor (continued). "Indeed, SEMA3A expression was found to decrease in advanced stage tumors, but other studies correlated high tumor levels of SEMA3A with poor outcome." (PMID 30658382, 2019). "Indeed, sema3F and sema3B have been characterized as bona fide tumor suppressors of lung cancer, and sema3A has been found to function as an endogenous angiogenesis inhibitor that is down-regulated during tumor progression." (PMID 30696103, 2019). "However, tumor cells-derived sema3A was also found to restrict the proliferation of pro-tumorigenic M2 macrophages and increase the proliferation of anti-tumorigenic M1 macrophages." (PMID 30696103, 2019). "Sema3A produced by tumor cells is also able to recruit bone marrow-derived cells to tumors." (PMID 30696103, 2019). "Sema3A expression is found in the central nervous system and other tissues and functions in the physiological and pathological processes, including axon guidance, cell migration, tumor growth, immune response, and angiogenesis." (PMID 31929841, 2019). "Whether SEMA3A can also directly control T cell function in the tumor context awaits clarification; however its regulatory activity on macrophages and dendritic cells is likely to impact adaptive anti-tumor immune response." (PMID 30658382, 2019). "Semaphorin 3A (Sema3A), a physiological ligand of Nrp1 (23, –, 25), inhibits in vitro dendritic cell (DC)-T cell interactions and tumor-T cell interactions, and by blocking Sema3A, hence suppressing the downstream signaling involving Nrp1, T cell activation and proliferation were restored." (PMID 31118303, 2019). "The expression of SEMA3A was influenced by tumor stage and gender of participants." (PMID 31205625, 2019). "Thus, Sema3A acts as a tumor suppressor, but its suppressor activity needs to be further explored and used in a potential therapeutic anti-tumor intervention." (PMID 30134791, 2018). "Thus, downregulation of SEMA3A expression was correlated with metastasis and poor tumour tissue differentiation." (PMID 29649113, 2018). "Furthermore, overexpression of Sema3A suppresses tumor growth and metastasis in vivo using xenograft mouse models." (PMID 28182100, 2017). "In light of the findings of this study, it is feasible that Sema3A may alter FAK phosphorylation at focal adhesions to regulate the cellular responses to changes in ECM composition of the stroma during tumor progression." (PMID 28182100, 2017). "Tumor xenografts model was used to evaluate the effect of Sema3a on the tumor growth." (PMID 28683823, 2017). "In addition to its involvement in cell motility and neuronal-vascular growth, Sema3A has also been ascribed with tumor-reducing capacities and anti-inflammatory properties during dermatitis, autoimmune arthritis and kidney injury." (PMID 28540528, 2017). "This massive recruitment of TAMs is usually facilitated by chemokines like CCL2, CCL5, VEGF, CSF-1, semaphorin 3A (SEMA3A), endothelin, eotaxin and oncostatin M. Once macrophages arrive in these tumour compartments, their migration is halted via hypoxia-dependent mechanisms." (PMID 29065107, 2017). "However, no results have been previously published that describe the relationship between Sema3A and tumor metastatic potential." (PMID 27351132, 2016). "We will, therefore, further investigate the effects of the tumor microenvironment on Sema3A." (PMID 27351132, 2016). "The up-regulation of cleaved-caspase-5 and caspase-7 provide further evidence of apoptosis, as do other findings that SEMA3A can sensitize tumor cells to curcumin, an anti-cancer agent that promotes apoptosis and poly ADP ribose polymerase (PARP) cleavage induced by SEMA3A." (PMID 26755661, 2016). "Sema3A also had an essential role in TAM recruitment in xenograft tumor models." (PMID 27351132, 2016). "Sema3A participates in both tumor progression and tumor suppression." (PMID 27351132, 2016). "SEMA3A also acts as a tumor suppressor because of its distinct antiangiogenic effects." (PMID 26755661, 2016).
tumor (continued). "It should be noted that other Nrp1-mediated pathways, particularly VEGFA, semaphorin 3A, and HGF signaling may also play important roles in the overall modalities of how GAMs associate with the tumor microenvironment." (PMID 26755653, 2016). "The localization of hypoxia-induced TAMs into hypoxic tumor areas is controlled by Sema3A." (PMID 27351132, 2016). "The results indicated that patients with higher Sema3A levels had greater tumor recurrence rates." (PMID 27351132, 2016). "Furthermore, we evaluated the relationship between SEMA3A expression and the clinical-pathological parameters of the tumor specimens." (PMID 26755661, 2016). "However, even for a single family member, such as Sema3A, an overall survey of the literature reveals data consistent with both tumour suppressive and tumour promoting roles." (PMID 25624520, 2015). "As VEGF is a key regulator of blood vessel formation, semaphorin-3A may prevent tumor progression by competitively inhibiting VEGF-induced tumor angiogenesis." (PMID 24765144, 2014). "The expression of semaphorin-3A was correlated with the maximum diameter of tumor." (PMID 24765144, 2014). "Therefore, lower expression of semaphorin-3A exhibited a more evident promoting effect on tumor growth." (PMID 24765144, 2014). "In addition, the expression of semaphorin-3A was correlated with the maximum diameter of the tumors; the lower the expression, the larger the maximum diameter of the tumor." (PMID 24765144, 2014). "Semaphorin-3A has been considered as a potent tumor suppressor in certain malignant neoplasms." (PMID 24765144, 2014). "These abnormal expression patterns may have an important role in tumor development and metastasis, and suggest that semaphorin-3A may be a suppressor gene and MMP-14 an oncogene." (PMID 24765144, 2014). "Semaphorin-3A has numerous diverse biological functions, including lymphocyte activation, vascular endothelial cell migration, lung and bronchial morphogenesis and promoting tumor cell migration." (PMID 24765144, 2014). "Interestingly, semaphoring 3A (Sema3A), an endogenous anti-angiogenic agent, counteracts sunitinib-induced tumor hypoxia, and Sema3A and sunitinib synergize to enhance survival of tumor-bearing mice." (PMID 24062984, 2013). "Thus, SEMA3A reduces the overall vascularity of tumors and “normalizes” tumor vessels, in part by recruiting myeloid cells that stimulate vessel maturation." (PMID 23475065, 2013). "In an accompanying study the authors showed there were larger amounts of doxorubicin in Sema3A-treated tumors, than controls, so Sema3A re-expression substantially extends the normalization window of tumor blood vessels and improves the delivery efficiency of chemotherapeutic drugs." (PMID 24102047, 2013). "The mechanism involved in the tumour inhibition by SEMA3A might relate to its interaction with integrins." (PMID 22926477, 2012). "SEMA3A is considered to be a candidate tumour suppressor in some cancers." (PMID 22926477, 2012). "Moreover, Semaphorin 3A (Sema 3A), another member of this family is shown to inhibit angiogenesis and acts as tumor suppressor." (PMID 22448259, 2012). "Class-3 semaphorins, such as sema3A, sema3B, sema3F have been previously characterized as natural tumor suppressors and there are indications that sema3E also may function as a natural tumor suppressor." (PMID 22936999, 2012). "Inhibition of integrins by SEMA3A could result in a blockade of endothelial and tumour cell migration, leading to reduced tumour angiogenesis and metastasis." (PMID 22926477, 2012). "By contrast, restoration of Sema3A expression in these cells normalizes intra-tumor vasculature, indicating that Sema3A could be used as a potential anti-angiogenic agent." (PMID 24212788, 2011). "Furthermore, in a very recent study using multiple murine models of tumorigenesis, Maione and collaborators showed that inhibition of sema3A in the later stages of carcinogenesis is responsible for enhanced angiogenesis and tumor progression." (PMID 24212788, 2011).
tumor (continued). "The np1 agonist sema3A also inhibits angiogenesis but it is as yet unknown whether it can inhibit tumor angiogenesis and tumor progression." (PMID 18818766, 2008). "The identification of sema3B and sema3F as tumor suppressors, and the identification of sema3F and sema3A as inhibitors of angiogenesis, suggested that additional sema3s may also possess anti-tumorigenic and anti-angiogenic properties." (PMID 18818766, 2008). "However, the expression of sema3A and sema3D, semaphorins that strongly inhibited tumor formation from these cells, also inhibited significantly the formation of large colonies in soft agar." (PMID 18818766, 2008). "Similarly, in hepatocellular carcinoma SEMA3A promoted tumor proliferation and migration." (PMID 38263416, 2024). "In addition, as A22p is derived from human semaphorin-3a and naturally binds to neuropilin receptors (NRPs) with high affinity, it was thus previously employed to promote the delivery of monoclonal antibodies by interacting with NPRs on tumor cells." (PMID 38409124, 2024). "First, we evaluated whether and how SEMA3A influenced tumour growth pattern and kinetics." (PMID 38670629, 2024). "Furthermore, a prior study indicated that SEMA3A may suppress angiogenesis and tumor growth in mice, suggesting its potential role in OSCC." (PMID 39177014, 2024). "Furthermore, we note that neuro-immune cell interactions could be observed in tumor-bearing mouse lungs in conjunction with the decreased expression of Sema3A." (PMID 36142564, 2022). "Furthermore, the expression of nerve elongation factor (NGF) was down-regulated in the PUVA-treated group, whereas that of semaphorin 3A (Sema3A), a nerve repulsive factor, was significantly up-regulated in the skin of AD patients and slightly elevated in the skin of dry skin model mice." (PMID 36015170, 2022). "The SEMA3A antibody developed by them significantly inhibited the migration and proliferation of GBM patient-derived cells and U87-MG cells in vitro, and inhibited tumor by down-regulating cell proliferation dynamics and tumor-associated macrophage recruitment in PDX model." (PMID 34630121, 2021). "Therefore, Sema3A could also help in the follow-up of patients following intravesical therapy as a non-invasive marker for tumor recurrence." (PMID 33546237, 2021). "Therefore, the role of SEMA3A as tumour suppressor needs to be reevaluated." (PMID 32241267, 2020). "In summary, our results indicate that SEMA3A, SEMA3C, SEMA3E, and SEMA3F are more often to promote tumorigenesis and associate with poor prognosis, while the other SEMA3s are more often to play a tumour suppressor role and generally associate with better prognosis." (PMID 32241267, 2020). "Moreover, Sema3A was also expressed in normal nasopharyngeal cells around the tumor cells." (PMID 32192122, 2020). "Thus, sema3A seems to modulate the recognition of tumor cells by the immune system." (PMID 30696103, 2019). "Furthermore, some of the class-3 semaphorins such as sema3A were characterized as natural inhibitors of angiogenesis whose down-regulation can enable the angiogenic switch that signals the onset of angiogenesis-dependent tumor progression." (PMID 30696103, 2019). "Moreover, the SEMA3A expression in patients with stage II was higher compared to patients with stage I. These results indicate that the SEMA3A may contribute to tumor progression." (PMID 31205625, 2019). "Interestingly, despite the anti-angiogenic properties of sema3A, some tumor cells express sema3A." (PMID 30696103, 2019). "Treatment with Sema3A switched tumor-associated immunosuppression toward immune activation, as documented from higher number of intratumoral inflammatory M1 type macrophages and increased proliferation of activated CD8+, NKT lymphocytes and significantly reduced tumor burden." (PMID 29067024, 2017). "However, given the complexity of the tumor microenvironment, this environment may also mediate the effects of Sema3A on tumor progression." (PMID 27351132, 2016).
tumor (continued). "In fact, when overexpressed at much greater than physiological levels through adeno-associated virus (AAV) vectors, Sema3A has been found to inhibit angiogenesis both by similarly overexpressed VEGF in AAV-treated muscles and by lower endogenous VEGF levels in tumor models." (PMID 26323572, 2015). "In addition, the expression of semaphorin-3A correlated with the maximum diameter of the tumor, while MMP-14 expression revealed no such association." (PMID 24765144, 2014). "Mike B Barnkob and his team reported that NRP1 KO mice and genetic models of Sema3A in cancer cells, T cell expression of NRP1, and tumor cell expression of Sema3A can control CD8+ T cell infiltration." (PMID 40277760, 2025). "Sema3A is produced in cancer cells and dysfunctional tumor-specific CD8+ T cells and can modulate anti-tumor response by upregulating NRP1, such as PD-1." (PMID 40277760, 2025). "Sema3A binds to Plexin A requires NRP1, found on CD4+ regulatory T-cells and tumor-infiltrating CD8+ T cells." (PMID 40277760, 2025). "SEMA3A and SEMA3F function as tumor suppressors, inhibiting neural invasion, angiogenesis, and metastasis by antagonizing neuropilin/plexin signaling." (PMID 41009819, 2025). "Therapeutic strategies that restore SEMA3A/3F signaling or inhibit SEMA3C, such as semaphorin analogs, Plexin B1-Fc decoys, and anti-SEMA3C antibodies, have shown promise in reducing tumor growth and neural infiltration in preclinical cancer models." (PMID 41009819, 2025). "Using T-cell-specific NRP1 knockout (KO) mice and genetic models of SEMA3A in cancer cells, we show that T cell expression of NRP1 and tumor cell expression of SEMA3A controls CD8+ T cell infiltration." (PMID 38609390, 2024). "Significantly more CD8+ T cells in both tumor and tumor-adjacent tissue expressed NRP1, suggesting that these cells would be sensitive to SEMA3A." (PMID 38609390, 2024). "In conclusion, we illustrated that NR2F2‐AS1 modulated the miR‐32‐5p/SEMA3A axis to attenuate EMT, migration, and invasion of OSCC cells, inhibit angiogenesis of HUVECs, and impede tumor growth and metastasis in mice." (PMID 39177014, 2024). "In this study, NR2F2‐AS1 overexpression elevated SEMA3A expression, blocked the EMT process, migration, and invasion of OSCC cells, inhibited angiogenesis of HUVECs, and suppressed tumor growth and metastasis in mice." (PMID 39177014, 2024). "Taken together, our data underscores the functional significance of SEMA3A within the TME as a potent inhibitor of CD8+ T cell migration, and thereby anti-tumor immunity, via interaction with NRP1." (PMID 38609390, 2024). "To further explore the effect of SEMA3A on CD8+ cell infiltration and localization, we compared regions within each tumor that were either SEMA3A rich or SEMA3A poor, allowing us to control for variability in CD8+ cell infiltration between patients." (PMID 38609390, 2024). "This signalling pathway consisted of three secreted proteins (SEMA3A, SEMA3B and SEMA3C), which were correlated with tumour metastasis and unfavourable therapy response." (PMID 39187937, 2024). "We show here that SEMA3A can be expressed by BEC and LEC cells in tumors, by some immune cells and also by the tumor cells themselves conditions." (PMID 38609390, 2024). "The present study suggests that NR2F2‐AS1 regulates the miR‐32‐5p/SEMA3A axis to inhibit EMT, migration, and invasion of OSCC cells and the angiogenesis of HUVECs, and to suppress tumor growth and metastasis in mice, thereby alleviating OSCC development." (PMID 39177014, 2024). "We find that the effects of SEMA3A on CD8+ T cells are mainly mediated through the co-receptor NRP1, which is retained on recently activated and tumor-specific T cells within the TME." (PMID 38609390, 2024). "The secreted protein genes WNT5A, VEGFA, and SEMA3A, and the receptor genes AXL, TNFRSF10B and IGF1R were mainly expressed by tumor cells." (PMID 37823774, 2023).
tumor (continued). "Blockage of the Sema3A/NRP1 axis via shRNA-mediated knockdown of Sema3A or NRP1 impeded clonogenic growth and TGF-β pathway activity in GSCs and inhibited tumor growth in vivo." (PMID 37788099, 2023). "Similar findings have also been reported in GBM, where the antibody blockade of SEMA3A was found to downregulate the PI3K/AKT pathway, inhibiting tumour growth and the recruitment of macrophages to the tumour site." (PMID 37685898, 2023). "SEMA3A and SEMA3B not only suppress tumor angiogenesis but also regulate immune cells in TME, including tumor-associated macrophages (TAMs)." (PMID 36942388, 2023). "For example, several SEMA3s (e.g. SEMA3A and SEMA3B) act as inhibitors of tumor progression, whereas SEMA3C exhibits both anti- and pro- tumorigenic effects." (PMID 36942388, 2023). "The relationship between the abundance of tumour-infiltrating lymphocytes (TILs) and the expression of EME1/HNRNPAB/PLAUR/SEMA3A in pan-cancer and LUAD was demonstrated on heatmaps and lollipop graphs." (PMID 36091160, 2022). "Subsequently, a study by Li and coworkers revealed that miR-192-5p can promote the proliferation and metastasis of the HCC cell line, HCCLM3, by targeting semaphorin 3A (SEMA3A), a potent inhibitor of tumor angiogenesis in different cancers." (PMID 33708127, 2021). "First, hypoxia-induced semaphorin 3A (Sema3A) and vascular endothelial growth factor (VEGF) act as chemoattractants for macrophages to the tumor microenvironment." (PMID 33670082, 2021). "Immunostaining and PCR analysis revealed that BTSCs highly express Sema3A and its receptors Nrp1 and PlxnA1, with expression of Nrp1 in the CD133 positive BTSCs, and absence in differentiated tumor cells." (PMID 33302912, 2020). "All other SEMA3 family members show inconsistent up- or down-regulation in different cancer tumours, where SEMA3B, SEMA3D, SEMA3E, and SEMA3G are primarily down-regulated, and SEMA3A and SEMA3C are mainly up-regulated in the tested cancer types." (PMID 32241267, 2020). "Whereas SEMA3A, SEMA3C, and SEMA3F were mainly up-regulated in the tested tumours, the rest of the members SEMA3B, SEMA3D, SEMA3E and SEMA3G were primarily down-regulated with a few exceptions." (PMID 32241267, 2020). "The expression levels of SEMA3A are also overexpressed in meningioma tissues, and the expression level is negatively correlated with the microvessel density (MVD) of the tumor." (PMID 32842711, 2020). "We next immunohistochemically analyzed SEMA3A expression and CD34 expression in the same tumor to evaluate the correlation of SEMA3A with the MVD." (PMID 32842711, 2020). "For instance, while SEMA3A binds specifically to NRP1 and SEMA3F binds to NRP2-containing holoreceptors to promote tumor cell normalization and inhibit metastasis in endothelial cells, SEMA3C shows similar affinities for NRP1 and NRP2." (PMID 32640719, 2020). "In general, our results show that SEMA3A, SEMA3C, and SEMA3F are primarily upregulated in cancer cells, while the rest of SEMA3s are mainly down-regulated in the tested tumours." (PMID 32241267, 2020). "An array of tumor-derived chemoattractants such as CSF1, CSF2, CCL2, VEGFA, and SEMA3A contribute to the recruitment of monocytic precursors, resulting in TAMs accumulation." (PMID 31406165, 2019). "Thus, manipulating Sema3A expression could have many beneficial effects in tumor therapy." (PMID 30134791, 2018). "A recent study showed that a rationally designed SEMA3A mutant, that elicits NRP1-independent signals via the plexin A4 receptor, is an effective anti-tumor agent." (PMID 30532711, 2018). "TAMs are recruited to hypoxic tumour areas by cancer cell-derived VEGF-A and semaphorin 3A through VEGFR1/neuropillin-1 signalling." (PMID 28210073, 2017). "Nevertheless, the mechanism by which SEMA3A modulates the expression pattern and activity of NRP1 and, consequently, the phenotype of the tumor requires further study." (PMID 26755661, 2016).